INS (insulin)
Diseases named in the same sentence as INS in open-access papers (continued):
Sharing a sentence is not in itself a finding about the gene and the disease.
steatosis (continued). "Thus, overall hepatic GR antagonism improved the insulin resistance but not the steatosis induced by a high-fat diet." (PMID 31199473, 2019). "In the absence of insulin, no steatosis occurs in PCLSs regardless of other medium components." (PMID 30818824, 2019). "The formation of steatosis in the in vitro system requires control of the insulin, FFA and monosaccharide concentrations at relevant physiological levels impossible to achieve in many common commercial cell media which can alter drug metabolism pathways and insulin sensitivity." (PMID 30250238, 2018). "Additionally, our data indicated that female SHROB rats elicited more efficient fatty acid transport (Cd36) and esterification (Pnpla3), and greater insulin sensitivity (higher phosphorylation of AKT and AMPK), all of which contributed to less severe steatosis." (PMID 30201044, 2018). "AMPK activation in the liver by 2-ME may explain the anti-steatosis and anti-insulin resistance effects of 2-ME, but it was not clear how 2-ME enhanced the secretion of insulin in mice under certain conditions." (PMID 28801594, 2017). "AlthoughVanin-1 plays a role in hepatic fatty acid oxidation, and that deviation to either side of normal may lead to steatosis, the contribution of Vanin-1 to the promotion of steatosis and insulin sensitivity in non-laboratory models is less clear." (PMID 27667588, 2016). "Furthermore, hepatic insulin signaling remains normal in HFD fed Pemt−/− mice despite profound steatosis with NASH features and TGH deficiency did not further affect insulin signaling." (PMID 27181051, 2016). "Furthermore, using a short term model of EtOH toxicity, pre-administration of insulin reduced oxidative stress and hepatocellular damage but did not diminish steatosis further demonstrating the contribution of insulin signaling in EtOH toxicity." (PMID 27124661, 2016). "According to the currently accepted hypothesis, inert TAG molecule itself probably does not interfere with insulin signaling but the negative effects of steatosis are mediated rather by bioactive intermediates of lipid metabolism like DAG or Lc-AcCoA." (PMID 22439764, 2012). "Conversely, the increased insulin sensitivity and decreased steatosis in the liver after treatment with Genz-112638 is not due to lowering ceramide levels, but rather may be a consequence of lowering GSL levels." (PMID 20574539, 2010). "Thus, in the absence of insulin, triglyceride is stored in the liver leading to steatosis." (PMID 29046730, 2017). "However, steatosis was removed in all tissues evaluated, and minimal levels remain in muscle and kidney cortex, but these do not have biological impact, because they mean a recovery of insulin resistance previously generated by HC consumption." (PMID 27119007, 2016). "Of note, measures of insulin clearance (CEACAM‐1 gene expression, IDE activity) did not correlate with measures of steatosis (MASLD scale, steatosis score, liver TG content)." (PMID 40476757, 2025). "Liver-specific receptor knockout mice demonstrated the importance of hepatic insulin signaling, with differential effects on VLDL secretion despite the absence of steatosis." (PMID 40723862, 2025). "In ob/ob mice, diet-induced NAFLD and steatosis were reversed by SREBP-1c antisense oligonucleotides, without improving insulin hepatic resistance." (PMID 38137501, 2023). "Previous studies have shown that GLP-1RAs act directly on human hepatocytes to decrease steatosis by preventing regeneration of fat and increasing oxidation of fatty acids and have shown that GLP-1RAs reduce IHA without insulin existed." (PMID 34956080, 2021). "The levels of glycemia, insulin, HbA1c, and HOMA-IR did not change with treatment among individuals with steatosis at both times." (PMID 34136497, 2021).
steatosis (continued). "Results from a small clinical study further reported increased liver EDA mRNA levels with increasing severity of steatosis and inflammation, and a negative correlation between liver EDA mRNA and whole-body insulin sensitivity." (PMID 33746906, 2021). "The authors claimed that ATGL ablation does not influence insulin sensitivity in hepatocytes despite induced marked steatosis, meanwhile, hepatic ATGL overexpression mildly improved hepatic insulin sensitivity without affecting hepatic inflammation." (PMID 35053204, 2021). "In the subcohorts of patients with steatosis, statin, insulin and PAD treatment was more frequent compared to the patients without steatosis." (PMID 31114547, 2019). "In the present study, we demonstrated that insulin and/or IGF1 signaling mediated through Irs1 is directly contributed to the development of HCC, independent of the development of steatosis." (PMID 28710407, 2017). "Subjects with steatosis had similar blood glucose, but higher insulin and C-peptide during OGTT than those without steatosis." (PMID 24732091, 2014). "Our results suggest that serum adiponectin levels were similar in CHB patients with or without steatosis; there were significant negative correlations between serum adiponectin, and BMI, FPG, serum insulin, serum c-peptide, and HOMA-IR." (PMID 23914225, 2013). "Disappointingly, even though rosiglitazone substantially improved steatosis in the first year, longer treatment did not improve NASH histology despite maintained effects on insulin sensitivity and ALT levels." (PMID 21918648, 2011). "RNA sequencing has demonstrated overall downregulation of insulin signaling genes in the liver of obese individuals with NAFLD and non-alcoholic steatohepatitis (NASH) liver samples compared with lean and obese controls without steatosis." (PMID 33498493, 2021). "Differential gene expression analyses indicate that reduction of steatosis by thiamine may involve destabilization of LDs and increased VLDL lipidation, rather than insulin sensitization." (PMID 33608323, 2021). "Hence, rather than presenting an insulin paradox (Section 2.2), the NAFLD / steatosis aspect of T2D reflects the double-edged activity of mTORC1 in promoting non-glycemic diseases of T2D while interfering with glycemic control." (PMID 32128655, 2020). "However, the development of MCD-induced steatosis is not dependent on DNL, since the MCD diet reduces the levels of insulin, glucose, expression of hepatic DNL enzymes, and hepatic DNL rate." (PMID 32411189, 2020). "Although previous studies have shown the role of insulin/IGF1 signaling and the downstream molecules in HCC development, the possibility of the effect of steatosis and surrounding hepatocellular damage could not be excluded in these studies." (PMID 28710407, 2017).
hyperlipidemia (704 papers, 2004 to 2026). "The development of insulin-deficient diabetes and hyperlipidemia, induced by streptozotocin injections combined with a 7-day hyperlipidemic diet, promotes AV remodeling." (PMID 41282350, 2025). "While the etiologies of hyperlipidemia on a KD are heterogenous, lower BMI and markers of insulin sensitivity are associated with larger increases as part of a triad of high LDL-C, high HDL-C, and low triglycerides known as the LMHR phenotype." (PMID 39296504, 2024). "Subsequently, during the late period of pregnancy, lipid catabolism is enhanced due to the insulin-resistant condition, which causes the development of maternal hyperlipidemia." (PMID 36615888, 2023). "Isotretinoin (13-cis RA) has been used to treat acne, but causes side effects such as hyperlipidemia and reduction of insulin sensitivity in human subjects, which was attributed to de novo lipogenesis." (PMID 37284305, 2023). "When GLU concentration increases, insulin ratio increases, and the excess glucose is stored in the subcutaneous fat, causing hyperlipidemia." (PMID 36911823, 2023). "In vivo, mice treatment with palmitate phosphorylates DDX1 and displaces it from the pre-proinsulin mRNA, suppressing insulin biosynthesis and indicating a direct link between hyperlipidemia and insulin deficiency." (PMID 35204710, 2022). "Since HFD causes hyperlipidemia and cardiovascular disease, we analyzed the blood composition, including insulin and leptin levels and lipid profiles in HFD-fed obese mice." (PMID 36145056, 2022). "Group III hyperlipidemia is caused in part by impaired insulin-mediated suppression of lipolysis in adipose tissue, which leads to β-cell apoptosis and ectopic hepatic lipid deposition." (PMID 35996069, 2022). "These animals with T1DM display weight loss, insufficient production of insulin, a high glucose level, and hyperlipidemia." (PMID 32393384, 2020). "In mice, in particular, palmitate-induced phosphorylation of DDX1 displaces it from the preproinsulin mRNA and suppresses insulin biosynthesis, hence providing a direct link between hyperlipidaemia and insulin deficiency." (PMID 32894308, 2020). "Due to these alterations, the lipoproteins and insulin absorption is compromised causing hyperlipidemia and hepatic insulin resistance." (PMID 32039217, 2019). "Taken together, our results suggest that Ln4 administration attenuates HFD-induced weight gain, hyperlipidemia, hepatic lipid accumulation, and insulin resistance by the regulating mRNA levels that are associated with glucose and lipid metabolism in the liver." (PMID 29783731, 2018). "It has become clear that rapamycin-based therapy causes many side effects, including thrombocytopenia, hyperlipidemia, impaired wound healing, nephrotoxicity, and altered insulin sensitivity." (PMID 30321984, 2018). "Aerobic fitness was also favorably associated with insulin sensitivity and lipemia, which provides additional evidence supporting the benefits of exercise in mitigating the adverse effects of unhealthy weight." (PMID 24714529, 2014). "Fenofibrate has been used in children for treating hyperlipidemia associated with Niemann-Pick disease, to improve insulin sensitivity and mitochondrial function following burn injury and as anti-angiogenic agent in children with brain tumors among others." (PMID 22514742, 2012). "The few studies that have examined complement C3 gene expression in adipose tissue have demonstrated associations with BMI, adipose tissue site, insulin sensitivity, age and postprandial lipemia." (PMID 20105310, 2010). "TCI904 effectively prevented fat and body weight accumulation without reducing food intake; it also modulated innate immunity and increased the level of IgA in feces, reversing the increased blood sugar and insulin levels and attenuated the hyperlipidemia caused by a HFD." (PMID 36345438, 2022).
hyperlipidemia (continued). "A dominant hypothesis is that the hyperlipidemia associated with overnutrition results in increased pancreatic insulin release and/or increased production of insulin-like growth factor 1 (IGF-1) in the liver." (PMID 34429409, 2021). "Another possible way to prevent the development of hyperlipidemia in susceptible animals might be to improve their insulin sensitivity." (PMID 34947937, 2021). "Elevated insulin levels usually cause hyperlipidemia in women with this syndrome." (PMID 34330312, 2021). "These plants were found to contain more than one bioactive compound that besides improving blood glucose levels also improved the associated hyperlipidemia, improved insulin secretion, exerted antioxidant effects, improved renal function, and also treated diabetic retinopathy and neuropathy." (PMID 31703341, 2019). "In conclusion, exposure to metformin in combination with H. cordata extract being enriched with high flavonoid and phenolic ingredients improved insulin sensitivity and hyperlipidemia which was associated with the reduction of endotoxin and inflammatory stress." (PMID 28937612, 2017). "Moreover, polymorphism in the APOA1-C3-A4 gene cluster was associated with hyperlipidemia and fasting insulin levels." (PMID 28549478, 2017). "Similarly, the present study demonstrated that age, medical history of hyperlipidemia, treatment with insulin and serum creatinine levels were significantly associated with cardiovascular events." (PMID 26842466, 2016). "Therefore, lower insulin level coupled with insulin resistance during diabetic condition causes hyperlipidemia." (PMID 27893829, 2016). "The weight loss in the ApoE−/− group may have been due to dysregulated AMPK signaling caused by hyperlipidemia, a feature observed in previous studied with hypertensive rats and insulin resistant rats." (PMID 26196300, 2015). "A follow-up study associated PD in captive Danish bank voles with the presence of ketonuria, ketonemia, hyperlipidemia, a major loss of insulin-positive beta cells, and autoantibodies against the same three markers (GAD65, IA-2, IAA) commonly used to predict human T1D." (PMID 21829666, 2011). "High doses of salicylates may have beneficial effects on reducing FPG, HbA1c level and increasing fasting insulin concentration, and may also have some positive effects on lipidemia and inflammation-associated parameters for patients with T2DM, without severe adverse effects." (PMID 28807030, 2017). "In both cases, lipemia-related laboratory interference complicated the initial evaluation, but prompt recognition and treatment with intravenous insulin led to rapid clinical and biochemical improvement." (PMID 42099341, 2026). "In contrast, it has been reported that insulin, heparin, and glucose injections are indicated during the therapeutic protocol of hyperlipidemia in donkeys." (PMID 40926229, 2025). "Community health care workers should pay attention to elderly diabetic patients with hyperlipidemia, insulin therapy, high glycated hemoglobin, and diabetic retinopathy to reduce the occurrence of foot ulcers." (PMID 40131908, 2025). "In another study, pu-erh tea was shown to cause a reduction in TG, cholesterol, insulin, and leptin levels while downregulating hepatic FAS mRNA and protein levels and enhancing AMPK phosphorylation in fructose-induced hyperlipidemia and hyperleptinemia." (PMID 40647906, 2025). "Extracts from teas exhibit antidiabetic properties by alleviating oxidative stress, managing hyperlipidemia, improving insulin sensitivity, and enhancing glucose tolerance." (PMID 40647906, 2025). "Binary Logistic regression analysis showed that age, glycosylated hemoglobin, hyperlipidemia, insulin therapy, and diabetic retinopathy were independent influencing factors for the occurrence of diabetic High-risk foot." (PMID 40131908, 2025). "Correspondingly, the insulin signaling pathway was revealed to be involved in the network pharmacology of GPA against hyperlipidemia." (PMID 40989883, 2025).
hyperlipidemia (continued). "Our Trpc1−/−mice demonstrate the following four features: increased body weight, elevated plasma glucose, increased plasma insulin, and hyperlipidemia." (PMID 38885005, 2024). "The current study confirms a decrease and sustained serum insulin levels in different doses compared to the hyperlipidemia‐induced group." (PMID 39479679, 2024). "The ability of USCP119 to reduce fat accumulation, improve lipid profiles, and enhance insulin sensitivity highlights its potential as a valuable dietary supplement for addressing high-fat diet-induced hyperlipidemia and metabolic disturbances." (PMID 39339790, 2024). "Adiponectin as a cardioprotective adipokine mediated insulin-sensitizing effects and reduces hyperlipidemia." (PMID 38566090, 2024). "RSG promotes healthier fat storage in adipose tissue, reduces lipemia, and enhances insulin sensitivity, particularly in males." (PMID 39339665, 2024). "The fundamental pathophysiological mechanisms of metabolic disorders are impaired insulin signaling, hyperlipidemia, the inflammatory response, and oxidative stress." (PMID 39049964, 2024). "In cardiology, physical activity is linked to various beneficial effects, such as lowering blood pressure, improving hyperlipidemia, and increasing insulin sensitivity." (PMID 39749313, 2024). "In the present study, HFD-induced hyperlipidemia was correlated with a significant increase in cortisol, insulin, NPY, and Y1 mRNA levels." (PMID 38645495, 2024). "While rehydration and continuous insulin infusion are fundamental components of DKA management due to the underlying insulin deficiency, the presence of severe hyperlipidemia with eruptive xanthomas warrants additional consideration." (PMID 38799544, 2024). "Meanwhile, the hyperlipidemia‐induced group experienced an increase in serum insulin due to decreased insulin sensitivity and increased insulin resistance." (PMID 39479679, 2024). "On the other hand, in rodents, RA treatment appears to improve insulin responses and correct obesity and hyperlipidemia." (PMID 37284305, 2023). "Mel effectively prevents hyperlipidemia by increasing insulin secretion and lipid storage in fat cells." (PMID 37005639, 2023). "Possible mechanisms by which MS affects renal physiology include impaired renal hemodynamics, insulin resistance, hyperlipidemia, activation of the renin–angiotensin–aldosterone system, inflammation, and oxidative stress." (PMID 37887410, 2023). "Treating mice with CAPE for five weeks ameliorated hyperlipidemia, insulin sensitivity, and PPARα levels." (PMID 37427329, 2023). "In subjects with acne and leukemia, RA treatment leads to hyperlipidemia and reduction of insulin sensitivity." (PMID 37284305, 2023). "The results showed that puerarin administration enhanced glucose tolerance and insulin sensitivity, while also mitigating liver dysfunction and hyperlipidemia in MAFLD mice." (PMID 38001459, 2023). "Hyperlipidemia, the number of diseased vessels, and insulin therapy were significantly higher in patients with MACEs related to NCLs, (p = 0.0098, p < 0.0001, and p = 0.0127, respectively)." (PMID 37034343, 2023). "In obese mice induced by feeding a high-fat/high-sucrose diet for 16 weeks, RA treatment reduced body weight, hyperlipidemia, and improved insulin responses, which was attributed to the activations of PPARβ/δ and RAR." (PMID 37284305, 2023). "ROS are produced in high amounts under hyperlipidaemia or exercise, and are thought to enhance metabolic-substrate handling, insulin sensitivity, and mitochondrial adaptation." (PMID 37812879, 2023). "In obese Wistar rats with T2DM, exogenous injection of adropin resulted in reduced blood glucose level, improved insulin sensitivity, ameliorated hyperlipidemia, and inhibited levels of inflammatory cytokines." (PMID 37079136, 2023).